MIR5739 (microRNA 5739)
Synonyms: hsa-mir-5739
Gene: MicroRNA gene on chromosome 22 (28,459,869 to 28,459,948, forward strand). Ensembl gene ENSG00000276162.
Homologues: Orthologues: chimpanzee MIR5739 (100% identical).